UQCC5 (ubiquinol-cytochrome c reductase complex assembly factor 5)
Description:
Required for the assembly and stability of the mitochondrial ubiquinol-cytochrome c reductase complex (complex III (CIII) or cytochrome b-c1 complex), a multisubunit transmembrane complex that is part of the mitochondrial electron transport chain (ETC) which drives oxidative phosphorylation (By similarity). Mediates early complex III biogenesis (By similarity). Participates in regulating the levels of electron transport chain proteins, and therefore energy supply, in response to changes in energy demand (By similarity). Also involved in the first steps of cytochrome c oxidase complex (complex IV) assembly.
Synonyms: C3orf78; SMIM4
Tractability: Antibody: UniProt predicts a signal peptide or a membrane-spanning region.
Gene: Protein-coding gene on chromosome 3 (52,533,950 to 52,579,237, forward strand). Ensembl gene ENSG00000168273.
Subcellular location: Mitochondrion inner membrane
Subcellular location (Human Protein Atlas): Mitochondria; Nucleoplasm
Pathways (Reactome):
Metabolism: Complex III assembly
Gene Ontology:
Molecular function: mitochondrial ribosome binding
Biological process: mitochondrial respiratory chain complex IV assembly; mitochondrial respiratory chain complex III assembly
Cellular component: mitochondrial inner membrane; mitochondrion
Genetic constraint (gnomAD): Loss-of-function variants: 4 observed, 5.59 expected, observed/expected ratio (o/e) 0.72, 90% interval 0.35 to 1.57. That is too few expected variants to judge how well the gene tolerates losing a copy. Missense variants: 51 observed, 67.38 expected, observed/expected ratio (o/e) 0.76, 90% interval 0.6 to 0.96. Synonymous variants: 24 observed, 28.09 expected, observed/expected ratio (o/e) 0.85, 90% interval 0.62 to 1.2.
Homologues: Orthologues: chimpanzee UQCC5 (100% identical), mouse Uqcc5 (94% identical), pig UQCC5 (93% identical), rabbit UQCC5 (93% identical), guinea pig UQCC5 (91% identical), dog UQCC5 (90% identical), macaque UQCC5 (76% identical), rat Uqcc5 (73% identical), zebrafish uqcc5 (61% identical), Drosophila melanogaster sloth1 (40% identical).
Diseases named in the same sentence as UQCC5 in open-access papers:
UQCC5 is named in the same sentence as 3 diseases in open-access papers, as found by Europe PMC text mining. Sharing a sentence is not in itself a finding about the gene and the disease.
UQCC5 shares sentences with these, for which no sentence is quoted: anxiety disorder (1 paper); lung adenocarcinoma (1); tumor (1).